EGFR (epidermal growth factor receptor)
Diseases named in the same sentence as EGFR in open-access papers (continued):
Sharing a sentence is not in itself a finding about the gene and the disease.
hepatocellular carcinoma (537 papers, 2001 to 2026). A malignant tumor that arises from hepatocytes. "Epidermal growth factor receptor (EGFR), rarely driven by oncogenic mutations (<5%) in hepatocellular carcinoma (HCC), soars in protein levels (> 60%)." (PMID 39206796, 2024). "Since hyperactivation of EGFR is frequently observed in hepatocellular carcinoma, which is associated with aggressive tumors and poor survival rates." (PMID 36348350, 2022). "BST2 has been shown to activate EGFR and the initiation of downstream signaling pathways by regulating its association with lipid rafts in hepatocellular carcinoma and to be involved in resistance to tumor cell death and chemotherapy." (PMID 35865015, 2022). "On the other hand, Egfr, that encodes for the epidermal growth factor receptor, is clearly underexpressed in hepatoma cells with respect to normal hepatocytes." (PMID 34737944, 2021). "β-catenin (CTNNB1) is more frequently mutated in men with hepatocellular carcinoma, and the activation of this proto-oncogene can affect sensitivity to EGFR, PI3K, AKT, and WNT inhibitors." (PMID 33330090, 2020). "Upregulation of miR-7 expression by the hepatitis B virus (HBV)-encoded HBx protein inhibits EGFR expression and controls the growth rate of hepatocellular carcinoma (HCC) cells." (PMID 32069901, 2020). "Macrophages associated with hepatocellular carcinoma have a high expression of epidermal growth factor receptor (EGFR), which induces IL6 signaling pathway, and hepatocyte proliferation being thus considered a tumor-promoting factor." (PMID 31921146, 2019). "For this reason, GALNT2 has been implicated in malignant control in hepatocellular carcinoma through modification of epidermal growth factor receptor (EGFR) glycosylation." (PMID 28025493, 2016). "The EGFR/PI3K/AKT signaling pathway has been proven to be associated with the ADAM17-mediated cisplatin resistance of hepatocellular carcinoma cells." (PMID 27313893, 2016). "The key signal transduction pathways that have been implicated in the pathogenesis of hepatocellular carcinoma are the EGFR, Ras/Raf/Mek/Erk, phosphoinositide 3-kinase/Akt, mTOR, HGF/c-Met, Wnt, and Hedgehog signaling cascades." (PMID 25895026, 2015). "The hepatitis B virus (HBV), the primary cause of hepatocellular carcinoma, upregulates EGFR expression and disrupts the fine tuning of EGFR-mediated signal transduction." (PMID 24340049, 2013). "In hepatocellular carcinoma, its misregulation was found in 60 to 80 percent of patients, depending on studies, leading to the suggestion that EGFR signaling upregulation was associated with the increased proliferative capacity of liver tumoral cells." (PMID 23050157, 2012). "This research found that among mammals and fishes, the microsatellite sequences are conserved in the genes of epidermal growth factor receptor, ataxia telangiectasia mutated and androgen receptor corresponding to cancers, ataxia telangiectasia and hepatocellular carcinoma, respectively." (PMID 25520927, 2014). "These newly described mutations may play a role in predicting response to EGFR-targeted therapy in hepatoma and their role should be explored in prospective studies." (PMID 17150109, 2006). "The combination of Semaminone and osimertinib demonstrated a synergistic growth inhibition in hepatocellular carcinoma (HCC) 827-osi resistant cells, suggesting a potential salvage therapy for EGFR mutation-mediated osimertinib resistance in NSCLC." (PMID 40841966, 2025). "In hepatocellular carcinoma (HCC), bypass activation of EGFR, VEGFR, and FGFR is implicated in mediating resistance to lenvatinib." (PMID 41275311, 2025). "According to a previous study, EGFR inhibition offers high-risk cirrhosis patients a promising treatment strategy for reducing fibrogenesis and preventing hepatocellular carcinoma (HCC)." (PMID 38560050, 2024). "HNK activates ERBB receptor feedback inhibitor 1 gene (ERRFI1) expression, encoded by ERRFI1, leading to EGFR inhibition in hepatocellular carcinoma (HCC)." (PMID 35453652, 2022).
hepatocellular carcinoma (continued). "It targets epidermal growth factor receptor (EGFR) mutation in hepatocellular carcinoma (HCC), effectively reducing HCC cell proliferation and sensitizing the tumor cells to sorafenib treatment." (PMID 34577576, 2021). "Genetic studies in mice reveal that loss of epidermal growth factor receptor (EGFR) in liver macrophages impaired hepatocellular carcinoma (HCC) formation whereas loss of EGFR in hepatocytes unexpectedly increased proliferation and thus led to HCC development." (PMID 27793010, 2016). "For example, modulating the codon frequency to regulate EGFR translation can maintain resistance to lenvatinib in hepatocellular carcinoma." (PMID 41501031, 2026). "The EGFR inhibition by erlotinib was found to overcome lenvatinib drug resistance in hepatocellular carcinoma by blocking the activation of the EGFR–STAT3–ABCB1 signaling pathway." (PMID 40551123, 2025). "For example, research has shown that Lnc-EGFR is crucial in Treg-mediated immunosuppression and the development of hepatocellular carcinoma (HCC)." (PMID 40739089, 2025). "In hepatocellular carcinoma, lnc-EGFR promotes immune evasion by stabilizing the EGFR protein, which enhances the downstream AP-1/NF-AT1 signaling pathway and drives Treg differentiation." (PMID 41221298, 2025). "The GALNT5 gene, part of the GALNT family, enhances EGF/EGFR activation in cancers like cholangiocarcinoma, hepatocellular carcinoma, and ovarian cancer." (PMID 40739397, 2025). "The unexpected finding that BRI3BP overexpression lowers lapatinib IC50 is consistent with earlier reports that ROCK-dependent cytoskeletal stress sensitizes hepatoma cells to EGFR inhibition." (PMID 41174063, 2025). "In this study, we mainly explored the inhibitory effect of Anshufacine hydrochloride on the growth of hepatoma cells and the EGFR/MAPK pathway." (PMID 40809022, 2025). "Another study proved that increased ZEB1‐AS1 contributes to enhanced bone metastasis in hepatocellular carcinoma via miR‐302b/EGFR/PI3K/AKT signaling pathway." (PMID 38783645, 2024). "The text-mining scores of CHI3L1, EGFR, and VEGF in hepatocellular carcinoma were 0.780, 0.393, and 0.785, respectively, indicating a higher association of CHI3L1 and VEGF in the disease than for EGFR." (PMID 38177294, 2024). "For its endosomal signaling, quiescin sulfhydryl oxidase 1 (QSOX1) has been identified as a cellular pro-oxidant, which accelerates ubiquitination-mediated degradation of EGFR and its intracellular endosomal trafficking in hepatocellular carcinoma (HCC) cells." (PMID 39456468, 2024). "This particular mechanism suggests that lnc-EGFR represents a potential therapeutic target for hepatocellular carcinoma (HCC), providing a solution to the intervention in HCC-related immune suppression." (PMID 39130630, 2024). "This study demonstratesthat these new sorafenib–ruthenium complexes inhibit the cellularproliferation of hepatocellular carcinoma cells and show EGFR enzymeinhibition." (PMID 38471014, 2024). "Conversely, other studies have shown that YTHDF2 inhibits cell proliferation and growth in hepatocellular carcinoma by destabilizing EGFR mRNA." (PMID 38397033, 2024). "A kinome-centered CRISPRko screen performed in the hepatocellular cancer (HCC) SNU449 cells highlighted the implication of EGFR in resistance to the multi-kinase inhibitor lenvatinib." (PMID 38255778, 2024). "Research on hepatocellular carcinoma has indicated that GOLM1 regulates EGFR/RTK recycling to encourage liver cancer cells to proliferate and spread." (PMID 39470578, 2024). "In this paper, we evaluate the roles of three entry factors in polarized hepatoma spheroids: epidermal growth factor receptor (EGFR) and tight junction proteins claudin-1 (CLDN1) and occludin (OCLN)." (PMID 38157366, 2023). "EGFR inhibition attenuates liver fibrosis and the development of hepatocellular carcinoma while restoration of EGFR rescues fatty liver regeneration in mice." (PMID 37156995, 2023).
hepatocellular carcinoma (continued). "We also compared the degradation performance of Nanosphere‐Ctx to that of siRNA‐mediated ASGPR knockout hepatoma cells and found that EGFR degradation was more pronounced in HepG2 and Huh7 cells that expressed ASGPR normally." (PMID 36866919, 2023). "Studies demonstrated that m6A binding protein YTHDF2 destabilized EGFR via binding to m6A site, and inhibited hepatocellular carcinoma cells." (PMID 36816363, 2023). "Additionally, the EGFR is implicated in the pathogenesis of both cirrhosis and hepatocellular carcinoma (HCC), with its hepatic expression increasing during cirrhosis." (PMID 38136237, 2023). "Using single particle imaging of HCV infection of polarized hepatoma spheroids, we observed that EGFR performs multiple functions in HCV entry, both phosphorylation-dependent and -independent." (PMID 38157366, 2023). "A significant role for EGFR has been demonstrated in liver regeneration following acute and chronic liver damage, as well as in cirrhosis and hepatocellular carcinoma, highlighting its importance in liver regeneration." (PMID 36817123, 2023). "Secreted HSPA5 also activated EGFR signaling and conferred the resistance of hepatocellular carcinoma (HCC) cells to sorafeinib." (PMID 37189349, 2023). "LncRNA-epidermal growth factor receptor (EGFR), which is upregulated in Tregs, promotes immune evasion of hepatocellular carcinoma by stimulating Treg differentiation and suppressing cytotoxic T lymphocyte (CTL) activation." (PMID 37744265, 2023). "In hepatocellular carcinoma, the epidermal growth factor receptor regulates YAP signaling through the PDK1 pathway to promote hepatocellular carcinoma cell growth." (PMID 37828220, 2023). "We find that EGFR performs multiple functions during HCV internalization into polarized hepatoma spheroids." (PMID 38157366, 2023). "Recently, EGFR inhibition showed promising results for preventing hepatocellular carcinoma in chronic HCV patients." (PMID 37967063, 2023). "In hepatocellular carcinomas, different signaling pathways are deregulated, such as the epidermal growth factor receptor (EGFR) expression pathway." (PMID 38069043, 2023). "EGF receptor (EGFR or HER1) is one of the most related growth factor receptors in hepatocellular carcinoma (HCC)." (PMID 37063954, 2023). "To study a possible impairment of EGFR activation upon ADAM10 inhibition in hepatoma cells, we assessed phosphorylation of ERK1/2 by antibody staining and flow cytometry." (PMID 37967063, 2023). "PLAGL2 was recently reported to promote hepatocellular carcinoma progression, metastasis and erlotinib tolerance via the EGFR signaling pathway." (PMID 36600208, 2023). "It has been reported that GOLM1 selectively interacts with EGFR and assists EGFR recycling back to the plasma membrane to drive hepatocellular carcinoma metastasis." (PMID 36841821, 2023). "EGFR is involved in the occurrence and progression of liver cirrhosis and hepatocellular carcinoma and the regeneration and repair of acute and chronic liver injuries." (PMID 35032098, 2022). "YTHDF2 inhibition promotes cell growth by reducing the m6A modification-induced degradation of EGFR mRNA in hepatocellular carcinoma (HCC) cells." (PMID 35669241, 2022). "Shao and co-workers developed polyamidoamine-aptamer-coated hollow MSNs to deliver the drug sorafenib and CRISPR/Cas9 to target epidermal growth factor receptor (EGFR) to, thus, enhance hepatocellular carcinoma C treatment." (PMID 35890389, 2022). "This is the first time in the world to use PD-1 monoclonal antibody combined with small molecule EGFR-TKI for first-line treatment in patients with advanced hepatocellular carcinoma, which achieved complete success." (PMID 36601120, 2022). "The overexpression of NTSR1 has been shown to indicate poor survival of patients with hepatocellular carcinoma and result in the activation of EGFR." (PMID 35251577, 2022).
hepatocellular carcinoma (continued). "Correspondingly, in the development of hepatocellular carcinoma, EGFR has been shown to elicit opposing physiological functions depending on cell type." (PMID 35732465, 2022). "Studies have shown that the use of EGFR inhibitors can limit the expansion of hepatocellular carcinoma." (PMID 36077440, 2022). "YTHDF2 is known to inhibit hepatocellular carcinoma cell proliferation and growth by inhibiting EGFR mRNA stability." (PMID 36479088, 2022). "Various studies have shown that the EGFR signalling pathway is involved in the occurrence and progression of liver cirrhosis and hepatocellular carcinoma and plays a crucial role in hepatocyte proliferation and liver regeneration." (PMID 35032098, 2022). "Mir-107 and CPEB3 interaction plays an important role in the occurrence and development of hepatocellular carcinoma by regulating the EGFR signaling pathway." (PMID 34879089, 2021). "It was found that the expression of ΔEx2p73 isoform is induced by activation of EGFR (epidermal growth factor receptor) by its ligand amphiregulin in human hepatocellular carcinoma cells and normal hepatocytes." (PMID 34207603, 2021). "The lncRNA lnc-EGFR can stimulate T-regulatory cells differentiation thus promoting hepatocellular carcinoma immune evasion." (PMID 34497315, 2021). "Study shows that Long noncoding epidermal growth factor receptor (lnc-EGFR) can promote hepatocellular carcinoma growth by inducing Treg differentiation, which offering a potential therapeutic target for hepatocellular carcinoma." (PMID 34288805, 2021). "New chimeric inhibitors targeting the epidermal growth factor (EGFR) and histone deacetylases (HDACs) were synthesized and tested for antineoplastic efficiency in solid cancer (prostate and hepatocellular carcinoma) and leukemia/lymphoma cell models." (PMID 34445133, 2021). "We also showed that GL and GlucoGL inhibited the interaction between PGRMC1 and EGFR in human hepatoma HuH7 cells." (PMID 34209885, 2021). "In esophageal cancer, YAP1 was found to mediate EGFR overexpression, while a reciprocal relationship was found in hepatocellular carcinoma, where EGFR induced expression of YAP1." (PMID 34944063, 2021). "Further investigations showed that GALNT4 attenuates the stemness and anchorage-independent survival of hepatocellular carcinoma cells in vitro and inhibits cancer cell growth in vivo partly via inactivating epidermal growth factor receptor (EGFR)." (PMID 33435156, 2021). "For example, high expression of GALNT1 promotes the acquisition of a malignant phenotype in hepatocellular carcinoma via Epidermal Growth Factor Receptor signaling." (PMID 35003361, 2021). "Here, we first analyzed two sets of clinical data and found that the levels of PGRMC1 and EGFR in hepatocellular carcinomas (HCCs) were both inversely correlated with the survival of HCC patients." (PMID 34069911, 2021). "Recently, a long noncoding RNA lnc-EGFR has been shown to stimulate Treg differentiation and promote immune invasion of hepatocellular carcinoma via an EGFR-dependent signaling pathway." (PMID 34113560, 2021). "Concomitantly, immune evasion of hepatocellular carcinoma (HCC) is supported by the lnc-EGFR, whose upregulation in tumor infiltrating CD4+ T cells also leads to their polarization into Treg cells." (PMID 34943820, 2021). "LINC01225/EGFR complex triggers the EGFR-dependent Ras/Raf-1/MEK/MAPK signaling pathway for metastasis in hepatocellular carcinoma." (PMID 33050646, 2020). "A study of the mechanism of hepatitis B virus- (HBV-) related hepatocellular carcinoma indicated that HBV-encoded X protein (HBx) induces HuR expression and mediates the increased stability of epidermal growth factor receptor (EGFR) mRNA." (PMID 32775456, 2020). "Both EGFR expression and phosphorylation were significantly increased in hepatoma cells compared to normal hepatocytes (1st panel from top, lanes 1–5, compared to lane 6)." (PMID 32298294, 2020).
hepatocellular carcinoma (continued). "Both DHW extract and the EGFR inhibitor SC0186 significantly inhibited the growth of hepatoma cells." (PMID 32298294, 2020). "In this study, we show for the first time that MYLK-AS1 promotes hepatoma cell proliferation, migration and invasion in vitro, and tumor formation in nude mice, through upregulation of EGFR and HER2 as well as their downstream targets." (PMID 32398965, 2020). "Regarding EGFR protein expression, EGFR overexpression promotes the migration of hepatocellular carcinoma expressing HBx." (PMID 32775456, 2020). "In contrast, in a separate model of hepatocellular carcinoma, PARP1 phosphorylation was dependent on the nuclear translocation of EGFR and formation of an EGFR/MET heterodimer causing MET activation." (PMID 32722408, 2020). "In the context of hepatocellular carcinoma, upregulation of epidermal growth factor receptor (EGFR) expression in regulatory T cells (Tregs) was found to contribute to tumorigenesis." (PMID 33182489, 2020). "As shown in a previous study, lnc-EGFR stimulates Treg differentiation and subsequently promotes the immune evasion of hepatocellular cancer." (PMID 32435615, 2020). "In contrast, the level of MET and EGFR were both decreased in TG hepatomas versus WT hepatomas, which was consistent with the findings in the liver regeneration model." (PMID 32489479, 2020). "Our research team previously identified PTPRS regulated EMT via dephosphorylation of EGFR in hepatocellular carcinoma." (PMID 33163494, 2020). "In the present study, we found that PKM2-induced phosphorylation of histone H3 is required for EGFR-mediated PD-L1 transcription in hepatocellular carcinoma." (PMID 33324209, 2020). "In sorafenib-resistant hepatoma cells, the efficacy of the treatment was increased when EGFR was inhibited by drugs (erlotinib or gefitinib), a monoclonal antibody directed against EGFR (cetuximab), and RNA interference." (PMID 32549224, 2020). "Golgi Membrane Protein 1 interacts with EGFR to promote EGFR recycling to the membrane, leading to prolonged EGFR activation and hepatocellular carcinoma progression." (PMID 32694521, 2020). "In this work, we analyze the role of calcium in human hepatoma (HCC) cell lines harboring a wild type form of the Epidermal Growth Factor Receptor (EGFR), particularly its role in proliferation and in EGFR downmodulation." (PMID 31635301, 2019). "For instance, LINC01225 promotes occurrence and metastasis of hepatocellular carcinoma by binding to EGFR and increasing the protein level of EGFR, then activating EGFR/MAPK signaling pathway." (PMID 31853225, 2019). "For example, lincRNA-Cox2 and lincRNA-NeST are regulators of innate immunity, and lnc-EGFR mediates immunosuppression in hepatocellular carcinoma by stimulating Treg differentiation." (PMID 31477638, 2019). "Deregulation of EGFR plays an important role in tumor progression of lung, breast, gastrointestinal, and liver carcinoma." (PMID 30202417, 2018). "A previous study showed that ITGB4 affected anoikis through interacting with EGFR in hepatocellular carcinoma." (PMID 30479571, 2018). "In HCC, downregulation of VPS37A promoted hepatocellular carcinoma cell migration and invasion by induction of EGFR activation and epithelial-mesenchymal transition." (PMID 29416742, 2018). "lnc-EGFR was shown to stimulate T-regulatory cells differentiation thus promoting hepatocellular carcinoma immune evasion." (PMID 30546835, 2018). "PTPN13 inhibited hepatocellular carcinoma through inactivation of the epidermal growth factor receptor (EGFR)/extracellular signal-regulated kinase (ERK) signaling pathway." (PMID 30001383, 2018). "For example, dysregulation of GALNT1 contributes to the malignant progression of hepatocellular carcinoma by modifying glycosylation of the epidermal growth factor receptor (EGFR), a member of receptor tyrosine kinase (RTK) family." (PMID 28388560, 2017).